NLGN3 (neuroligin 3)
Description:
Cell surface protein involved in cell-cell-interactions via its interactions with neurexin family members. Plays a role in synapse function and synaptic signal transmission, and may mediate its effects by clustering other synaptic proteins. May promote the initial formation of synapses, but is not essential for this. May also play a role in glia-glia or glia-neuron interactions in the developing peripheral nervous system (By similarity).
Synonyms: KIAA1480; HNL3; ASPGX1; AUTSX1
Tractability: Small molecule: it belongs to a druggable protein family. Antibody: its Gene Ontology location is reachable by antibodies, with high confidence; UniProt places it where antibodies can reach, with medium confidence; UniProt predicts a signal peptide or a membrane-spanning region. PROTAC: its protein half-life has been measured.
Gene: Protein-coding gene on chromosome X (71,143,286 to 71,175,255, forward strand). Ensembl gene ENSG00000196338.
Subcellular location: Cell membrane; Synapse; Cell projection, dendrite
Subcellular location (Human Protein Atlas): Cell Junctions; Golgi apparatus
Pathways (Reactome):
Neuronal System: Neurexins and neuroligins
Gene Ontology:
Molecular function: protein binding; scaffold protein binding; cell adhesion mediator activity; cell adhesion molecule binding; neurexin family protein binding; signaling receptor activity
Biological process: adult behavior; learning; social behavior; synapse organization; vocalization behavior; axon extension; chemical synaptic transmission; inhibitory postsynaptic potential; modulation of chemical synaptic transmission; neuron cell-cell adhesion; positive regulation of excitatory postsynaptic potential; positive regulation of glutamate receptor signaling pathway; positive regulation of synapse assembly; positive regulation of synaptic transmission, glutamatergic; postsynaptic membrane assembly; presynapse assembly; presynaptic membrane assembly; receptor-mediated endocytosis; regulation of respiratory gaseous exchange by nervous system process; rhythmic synaptic transmission; synapse assembly; synaptic vesicle endocytosis
Cellular component: cell junction; cell surface; excitatory synapse; asymmetric, glutamatergic, excitatory synapse; dendrite; endocytic vesicle; membrane; plasma membrane; postsynaptic membrane; symmetric, GABA-ergic, inhibitory synapse; synapse; neuron to neuron synapse; presynapse
Gene-disease validity (ClinGen):
ClinGen rates the evidence that NLGN3 causes each of these diseases.
X-linked complex neurodevelopmental disorder (X-linked): Moderate. A complex neurodevelopmental disorder that is transmitted via X-linked inheritance, and is characterized by intellectual disability, autism and epilepsy.
Homologues: Orthologues: chimpanzee NLGN3 (99% identical), macaque NLGN3 (99% identical), pig NLGN3 (99% identical), guinea pig NLGN3 (99% identical), dog NLGN3 (99% identical), rat Nlgn3 (99% identical), mouse Nlgn3 (99% identical), rabbit NLGN3 (97% identical), tropical clawed frog nlgn3 (85% identical), zebrafish nlgn3a (84% identical), Drosophila melanogaster Jhe (19% identical), Caenorhabditis elegans ace-4 (18% identical), and 40 more. Paralogues in human: NLGN4X (70% identical), NLGN4Y (70% identical), NLGN1 (68% identical), NLGN2 (62% identical), CES1 (23% identical), CES4A (23% identical), CES2 (22% identical), CES3 (22% identical), CES5A (22% identical), ACHE (22% identical), BCHE (21% identical), TG (21% identical), and 1 more.
Diseases named in the same sentence as NLGN3 in open-access papers:
NLGN3 is named in the same sentence as 54 diseases in open-access papers, as found by Europe PMC text mining. Sharing a sentence is not in itself a finding about the gene and the disease. The quoted sentences say what the papers report.
autism (111 papers, 2005 to 2026). Persistent deficits in social interaction and communication and interaction as well as a markedly restricted repertoire of activity and interest as well as repetitive patterns of behavior. "Neuroligin-3 (Nlgn3) is an autism-associated cell-adhesion molecule that interacts with neurexins and is robustly expressed in both neurons and astrocytes." (PMID 39003414, 2025). "Leveraging our astroglia-enriched organoid models, which exhibit enhanced NRXN-NLGN signaling, we employed hESCs carrying the NLGN3 R451C mutation to develop organoids and further explore astroglial pathology in autism." (PMID 39775628, 2025). "In conclusion, these results suggest that the autism-associated NLGN3 R451C mutation promotes astrogliogenesis and advanced astroglia morphology in astroglia-enriched organoids, indicating a potential gain-of-function phenotype." (PMID 39775628, 2025). "As proof of concept, we generated astroglia-enriched organoids from human embryonic stem cells (ESCs) carrying the autism-associated NLGN3 R451C mutation." (PMID 39775628, 2025). "To further investigate astrocytic functions in this pathway, we introduced an autism-associated NLGN3 R451C mutant embryonic stem cell (ESC) line to generate astroglia-enriched organoids." (PMID 39775628, 2025). "Mice expressing the autism-associated R451C variant encoding Neuroligin-3 (Nlgn3), a membrane protein located at neuronal synapses, show GI dysfunction, microbial dysbiosis and reduced macrophage density in caecum." (PMID 40036582, 2025). "The NLGN3 R451C mutation is the first autism-associated mutation identified in patients, and studies in mouse and human neurons have shown that this mutation contributes to autism-related phenotypes through a gain-of-function mechanism." (PMID 39775628, 2025). "Recent research has linked the biology of autism to mutations in the X-linked neuroligin genes NLGN3 and NLGN4." (PMID 41245836, 2025). "In summary, the autism-associated R451C variant in the Neuroligin-3 gene increases mucus density adjacent to the epithelium and alters microbial spatial distribution in the mouse distal ileum." (PMID 40036582, 2025). "We further discovered that brain organoids derived from human embryonic stem cells (hESCs) harboring the autism-associated NLGN3 R451C mutation exhibit increased astrogliogenesis." (PMID 39775628, 2025). "Research suggests that the Nlgn3 R451C mutation, associated with autism, reduces Nlgn3 mRNA expression in cholinergic enteric neurons, potentially disrupting gut–brain communication and contributing to gastrointestinal disturbances in ASD." (PMID 40150580, 2025). "Our findings indicate that mice expressing an autism-associated mutation in the gene encoding the Neuroligin-3 protein display gut dysfunction." (PMID 38255906, 2024). "In all, these findings suggest that the autism-associated R451C missense mutation in the Nlgn3 gene impacts the structure and function of the mouse gastrointestinal tract." (PMID 38255906, 2024). "A missense mutation in the Nlgn3 gene encoding the cell adhesion protein Neuroligin-3 was identified in two brothers with autism who both experienced severe gastrointestinal dysfunction." (PMID 38255906, 2024). "Autism-associated neuroligin-3 deficiency in medial septum causes social deficits and sleep loss through divergent downstream circuit targets." (PMID 39058792, 2024). "In mouse models, protein translation deficiencies have also been linked to autism-associated variants in the synaptic adhesion molecule neuroligin-3 (NLGN3)." (PMID 36979972, 2023). "Mutations in the NLGN3 gene, including the missense R451C point mutation as well as NLGN3 deletion, are implicated in autism." (PMID 37509099, 2023). "Here, we characterised Nlgn3 mRNA expression and identified effects of the autism-associated R451C mutation in this gene in the enteric nervous system of the mouse ileum." (PMID 37509099, 2023).
autism (continued). "We also assessed for changes in neurochemical markers and Nlgn3 gene expression in the enteric nervous system of mice expressing the R451C autism-associated mutation in Nlgn3." (PMID 37509099, 2023). "In summary, our findings suggest that the autism-associated Neuroligin-3 R451C mutation alters gastrointestinal secretory function via a nAChR-mediated pathway in the submucosal plexus." (PMID 37542090, 2023). "Here, we studied mice with an autism-associated missense mutation in the post-synaptic protein neuroligin-3 (Nlgn3R451C), which impacts brain and enteric neuronal activity." (PMID 37542090, 2023). "It has also been reported that NLGN3-R451C mice (an ASD-associated mutation) displayed enhanced spatial learning in the Morris water maze in addition to autism-like behaviors." (PMID 34848499, 2022). "PTCHD1 and NLGN3 are associated with susceptibility to autism in OMIM, but both were recently confirmed to cause a monogenic ID disorder frequently associated with autism." (PMID 36323681, 2022). "Here, we deconstructed the role of neuroligin-3 (Nlgn3), a postsynaptic adhesion molecule linked to autism, in organizing AMPA-type glutamate receptors in the calyx of Held synapse." (PMID 35704570, 2022). "This potential species difference would be problematic to examine as human patients with the R451C mutation are rare and NLGN3-R451C human autism patient stem cell lines have yet to emerge." (PMID 34542148, 2022). "For example, a missense mutation in the neuroligin 3 (Nlgn3) protein was identified in autism patients." (PMID 35846755, 2022). "Both Nlgn3 loss-of-function and the Nlgn3 autism-associated R451C mutation affect social behaviors in mice, although with some differences." (PMID 35601025, 2022). "The association of Nlgns with autism was first reported in a Swedish family with two affected siblings, where one of the siblings had a de novo missense mutation in the coding region of Nlgn3 and the other in Nlgn4X." (PMID 35601025, 2022). "For example, multiple autism-associated synaptic proteins, including Nlgn3, Shank3, and FMRP, affect group-I or group-5 metabotropic glutamate receptors (mGluRs)." (PMID 35601025, 2022). "Nlgn3 knock-in mice harboring the autism-related R451C mutation (Nlgn3R/C) and Nlgn3 knockout (KO) mice display enhanced ability to remain on the accelerating rotarod associated with the repetitive behaviors of ASD11." (PMID 33758193, 2021). "Variants in neuroligin 1 and SHANK2 have been implicated in susceptibility to autism, while variants in neuroligin 3 have been implicated in Asperger syndrome and autism." (PMID 34610269, 2021). "Several missense variants in NLGN3 account for non-syndromic forms of intellectual disability associated with autism." (PMID 35012288, 2021). "In the present study, we show that an autism-associated genetic mutation of NLGN3 affects developmental synaptic refinement in the mouse cerebellum." (PMID 34262438, 2021). "Mice expressing the Neuroligin-3 R451C mutation exhibit autism-relevant behaviors including impaired social interaction, a heightened aggression phenotype, impaired communication and increased repetitive behaviors." (PMID 32327975, 2020). "Mutations in genes encoding synaptic adhesion proteins such as the R451C missense mutation in neuroligin-3 (NL3) are associated with autism and impair synaptic transmission." (PMID 32327975, 2020). "Here, we identify changes in both the nervous system and immune system caused by an autism-associated mutation in Nlgn3 encoding the postsynaptic cell adhesion protein, Neuroligin-3." (PMID 32327975, 2020). "We generated Nlgn3y/−Cyfip1+/− double-mutant mice to investigate the effect of the Nlgn3/Cyfip1 pathway on phenotypes associated with autism: changes in behavior and dendritic spine density." (PMID 32669345, 2020).
autism (continued). "Increased inhibition was observed in the somatosensory cortex of mice expressing the R451C autism-related mutation in NLGN3, and this was associated with impairments in social interaction." (PMID 28468253, 2017). "In conclusion, we show that in our inducible PC12 model system, partial misfolding caused by the R451C autism-linked mutation in NLGN3 activated the UPR." (PMID 26621873, 2016). "Further studies, performed on a greater number of patients and with different genetic backgrounds, will be required to elucidate the role of NLGN3 in autism susceptibility." (PMID 27782075, 2016). "The R451C single point mutation in NLGN3, an X-linked gene, was found in association with highly penetrant autism in a Swedish family." (PMID 26621873, 2016). "In the present study, we focused on the R451C variant of NLGN3, which is the best characterized autism-linked mutation in the neuroligin family." (PMID 26621873, 2016). "In mouse models, autism-associated NLGN3 mutations induced repetitive behaviors, and R451C mutant mice showed impaired social interactions, but enhanced spatial learning abilities." (PMID 27782075, 2016). "A single, maternally inherited, X-linked point mutation leading to an arginine to cysteine substitution at amino acid 451 (R451C) of Neuroligin 3 (NLGN3R451C) is a likely cause of autism in two brothers." (PMID 26469287, 2015). "An autism-associated point mutation in Neuroligin 3 (Nlgn3) resulting in an amino acid change from arginine to cysteine at residue 451 (R451C) has been successfully replicated in a genetic mouse model." (PMID 26469287, 2015). "Our data provide further evidence that coding sequence mutations at NLGN3 or NLGN4X that cause autism are very rare." (PMID 23020841, 2012). "Disruption of cell-adhesion molecules is a common theme emerging from autism genetic studies, including a point mutation in neuroligin-3 (R451C), and mutations in Shank-3." (PMID 21826280, 2011). "Further, mutations in cell adhesion genes NLGN4 on Xp22.3 and NLGN3 on Xq13 are reported in patients with autism." (PMID 15655077, 2005). "Neuroligin-3 is a synaptic adhesion molecule that has been linked to autism and GI distress." (PMID 40801603, 2025). "A mouse model of an autism-linked variant in neuroligin-3 R451C shows diverse gut phenotypes, including faster transit, increased numbers of myenteric neurons in the small intestine, increased mucous layer density in the distal ileum epithelium with an associated change in microbial distribution." (PMID 40801603, 2025). "Autism caused by mutationsin the neuroligin-3 (NLGN3) gene may be accompanied by neuronal oxidative stress.Nevertheless, no prior research has been carried out on the impact of theNL3R617W mutation in in vitro and in vivo modelsof autism." (PMID 40071366, 2025). "Here, we analysed the spatial distribution of the mucin-2 protein using immunofluorescence as well as total bacteria, Bacteroidetes, Firmicutes phyla, and Akkermansia muciniphila using fluorescent in situ hybridization in mice expressing the autism-associated R451C variant in the Neuroligin-3 gene." (PMID 40036582, 2025). "In addition, we uncover a novel genetic and isoform interaction in behavior with the conserved gene, nlg-1/NLGN3, which is also associated with autism." (PMID 38036526, 2023). "In addition, we report that the autism-associated Nlgn3 R451C mutation reduces Nlgn3 mRNA expression in both submucosal and myenteric neurons as well as myenteric glia in the mouse ileum." (PMID 37509099, 2023).
autism (continued). "Characterising Nlgn3 expression in enteric cell subtypes is essential for identifying underlying mechanisms contributing to GI activity and to functional GI changes observed in patients and the Nlgn3R451C mouse model of autism." (PMID 37509099, 2023). "Regardless of direct vs. indirect molecular effects, our data indicate that abnormalities in transmission at PP-GC synapses may contribute to the consequences of loss-of-function variants of Nlgn3 on autism-related behavioral phenotypes." (PMID 34845591, 2022). "Here we assessed whether the autism-associated R451C mutation in Neuroligin-3 affects gross caecal morphology, enteric neuronal populations or immune cells within the caecal patch." (PMID 32327975, 2020). "Also, mice with autism-linked neuroligin-3 R451C mutation show impaired social interactions accompanied by an altered inhibitory synaptic transmission." (PMID 30846682, 2019). "Arg451Cys (R451C) missense mutation of NLGN3 has been associated with autism in humans." (PMID 28880200, 2017). "The goal of the present study was to understand whether the autism-associated R451C NLGN3 protein elicits ER stress and UPR activation in mammalian cells." (PMID 26621873, 2016). "Perhaps the best studied mouse model based on the NLGN genes that is relevant to autism are the NLGN3 knock-in (KI) mice harboring the R451C missense mutation (i.e., Arg451 is substituted with Cys451) because this mutation was shown to be linked to autistic patients." (PMID 27047540, 2016). "Neuroligin-3 mutations associated with autism disrupt endocannabinoid signaling." (PMID 25885783, 2015). "We next sought to determine whether any of the four rare, intronic variants in NLGN3 could act as autism susceptibility alleles." (PMID 23020841, 2012). "This study indicates that the Nlgn3 R451C variant impacts mucus layer structure and composition; however, further work is necessary to elucidate the resulting microbial community level changes to function and biological mechanisms underlying neurally mediated mucus regulation in autism." (PMID 40036582, 2025). "We provide a comprehensive cellular profile for neuroligin-3 expression in ileal neuronal subpopulations of mice expressing the R451C autism-associated mutation in Nlgn3, which may contribute to the understanding of the pathophysiology of GI dysfunction in ASD." (PMID 37509099, 2023). "Taken together, these findings suggest that NLGN3 is an important component of neuronal and neuron–glial communication in the gut and that mutations in NLGN3 might play a role in GI dysfunction in individuals with autism." (PMID 37509099, 2023). "Furthermore, Nlgn3 knockout (KO) rats and mice, as well as mice with an autism-associated Nlgn3 mutation, exhibit ASD-related behavioral abnormalities such as reduced sociability, impaired social memory, decreased vocalization, increased repetitive behaviors, and hyperactivity." (PMID 34845591, 2022). "In addition, NLGN3 deficiency has been also associated with autism-like behaviors." (PMID 28880200, 2017). "In the present study, we examine the neuroligin‐3 (NLGN3) R451C mouse model (NL3) of autism during the performance of non‐social tasks of reward motivation." (PMID 40816723, 2025). "Arginine‐to‐cysteine substitution at amino acid position 451 (R451C) of NLGN3 was first identified in two brothers with non‐syndromic autism, inherited from their non‐autistic heterozygotic mother." (PMID 40816723, 2025). "Recently, changes in dPAG excitability and the expression of defensive behaviours have also been identified in the Nlgn3+/− rat model of autism." (PMID 38857283, 2024). "Numerous studies support a strong genetic component in the development of autism, with links to mutations involving specific genes such as SHANK3, NLGN3, and NRXN1." (PMID 38435203, 2024). "Other variants (SNVs and CNVs) in NLGN1 and/or other family members NLGN3 and NLGN4 were previously associated with PTSD, autism, obsessive-compulsive disorder, and depression." (PMID 36253440, 2023).